IL6 (interleukin 6)
Diseases named in the same sentence as IL6 in open-access papers (continued):
Sharing a sentence is not in itself a finding about the gene and the disease.
Arthritis (continued). "Cytokines such as TNF-α, IL-1β, and IL-6 induce joint inflammation and upregulate the production of MMPs (1, 2, 3, 7, 8, 9, and 13) through inflammatory signaling." (PMID 40427394, 2025). "These conjugates significantly suppressed synoviocyte proliferation and IL-6 secretion, and preferentially accumulated in inflamed joints in a collagen-induced arthritis rat model, supporting their targeted delivery and therapeutic potential." (PMID 40563345, 2025). "Studies in mice have also shown that BBR can improve the clinical symptoms of various types of arthritis by downregulating the expression levels of inflammatory factors, such as IL-1β, IL-6, and TNF-α." (PMID 40829428, 2025). "In CIA mice, triptolide changed serum E2 and FSH levels, the estrous cycle, arthritis scores, IL-6, and IL-17A levels." (PMID 40918529, 2025). "These flavonoids demonstrate potent anti-inflammatory properties by inhibiting prostaglandin E2 synthesis and modulating cytokines like TNF-α and IL-6, offering promise for chronic inflammatory conditions such as arthritis." (PMID 40870742, 2025). "We detected varying concentrations of IL-6 in the SF of patients with IA depending on the type of arthritis." (PMID 40687784, 2025). "The rams with arthritis showed significantly greater levels of gene expression for the genes IL-1α, IL-1β, IL-6, IL-10, TNFα, NCF4, NFKB, TMED, FCAMR, iNOS and COX18 than did the healthy rams." (PMID 40005882, 2025). "Therapeutic effects were assessed via arthritis index, paw swelling, and serum cytokines (IL-1β, IL-6, IL-17A)." (PMID 40864815, 2025). "For example, in a collagen-induced arthritis model, tocilizumab reduced inflammatory markers but induced liver collagen deposition, highlighting a dual role of IL-6 in both inflammation and tissue remodeling." (PMID 40693271, 2025). "Preclinical studies demonstrate its potent anti-inflammatory effects by inhibiting prostaglandin E2 synthesis and modulating cytokines like TNF-α and IL-6, suggesting applications for chronic inflammatory disorders such as arthritis." (PMID 40870742, 2025). "Intriguingly, while IL-6 neutralization ameliorates arthritis, TNF blockade shows inconsistent therapeutic efficacy." (PMID 41583484, 2025). "It was observed that even the lowest dosage of 0.125% CLA was sufficient to decrease plasma cytokines (IL-1β, TNF-α, IL-6) and reduce arthritis symptoms (paw swelling and clinical scores) by the end of the 84-day trial." (PMID 40806004, 2025). "IL-6 initiates cellular signaling through both membrane-bound and soluble receptor forms, contributing to inflammation and joint destruction in arthritis." (PMID 40153574, 2025). "The NRF2 inducer sulforaphane was demonstrated to have an anti-arthritis effect by inhibiting PC differentiation and production of inflammatory cytokines (IL-6, IL-17, TNFα etc.)." (PMID 39875809, 2025). "Gene expression intensities were much higher in the arthritis-affected rams than in the healthy ones for the genes IL-1α, IL-1β, IL-6, IL-10, TNFα, NCF4, NFKB, TMED, FCAMR, iNOS and COX18." (PMID 40005882, 2025). "The Soufeng sanjie formula (centipede, scorpion, and additional herbs) likewise ameliorated arthritis by decreasing IL-6, TNF-α, and IL-17 and reestablishing the Th17/Treg balance." (PMID 40423312, 2025). "Thiamet-G, another O-GlcNAcase inhibitor, has been shown to increase O-GlcNAc-modified proteins and reduce the production of pro-inflammatory cytokines (IL-6 and IL-8) in arthritis." (PMID 41300284, 2025). "When comparing healthy rams to those with arthritis, the expression levels of the following genes were noticeably higher: IL-1α, IL-1β, IL-6, IL-10, TNFα, NCF4, NFKB, TMED, FCAMR, iNOS and COX18." (PMID 40005882, 2025). "It will be important to characterize the underlying mechanism of the DUSP6 regulation on IL10 and IL6 expression, as well as DUSP6-specific target signaling pathways in arthritis." (PMID 38974475, 2024).
Arthritis (continued). "Taken together, our findings suggest that combination of LMT-28 and kaempferol synergistically regulates IL-6-induced hyperactivation of synovial cells and can be an alternative option for arthritis treatment." (PMID 39083495, 2024). "Considering that IL-1β is both an upstream and downstream gene of NF-κB, the present data indicate that baricitinib suppressed the IL-6 Amp, the amplification of these two pathways mediated by IL-6, during arthritis." (PMID 38879555, 2024). "This protection is partly explained by NBQX inhibiting AMPA/KA GluR release of interleukin-6 (IL-6), an early driver of inflammation in both models of arthritis." (PMID 39157681, 2024). "For example, certain cytokines such as interleukin-1β (IL-1β), tumor necrosis factor-α (TNF-α), and interleukin-6 (IL-6) have been identified as key regulators in OA development and arthritis inflammation." (PMID 38496843, 2024). "Technical advances in special transcriptomics will help us understand the spatiotemporal relationships among OSM+ macrophages, OSMR+ fibroblasts, IL-6+ fibroblasts and IL-6R+ macrophages in the inflamed synovium during the course of arthritis in future." (PMID 39080781, 2024). "GCSF, IL-6 and BLC all have established roles in immune cell recruitment and joint degeneration in arthritis (57, –59), IL-6 is additionally thought to directly sensitize sensory neurons to induce mechanical and thermal hypersensitivity." (PMID 39661058, 2024). "Chronic CHIKV arthritis is characterized by significantly higher IL-6 than found in recovered patients." (PMID 38507338, 2024). "Studies in patients with arthritis showed that W-BC helped reduce inflammatory markers such as IL-6, tumor necrosis factor, and serum CRP." (PMID 39576692, 2024). "In vivo experiments confirmed the favorable effects of quercetin in CIA rats, including an improved arthritis score and reduced ankle bone destruction, in addition to a decrease in the pro-inflammatory cytokines IL-1β, IL-6, IL-17, and TNF-α in serum." (PMID 39390367, 2024). "Irradiation of 0.1 sub-THz alleviated arthritis symptoms and reduced the expression of several pivotal proinflammatory cytokines, including IL-6, TNF-α, IL-1b, and IL-17 in CIA mice." (PMID 38892148, 2024). "Mechanistic studies on IL-6-induced signaling pathways in RA-FLS suggested that the combination of LMT-28 and kaempferol has a significant effect on hyperactivation of IL-6-related activities in arthritis." (PMID 39083495, 2024). "We also demonstrate that the YEO treatment reduced IL-6 levels in the synovial fluid of the mice submitted to zymosan-induced arthritis." (PMID 39194751, 2024). "Further, fecal microbiota transplantation (FMT) from P. gingivali-inoculated experimental arthritis mice reproduced donor gut microbiota and resulted in severe joint destruction with increased IL-6 and CP production in joint and intestinal tissues." (PMID 39619660, 2024). "Taken together, these data suggest that baricitinib greatly suppressed arthritis-induced inflammatory and neuropathic pain through the inhibition of IL-6 Amp and the subsequent decrease in Csf1 expression in DRG." (PMID 38879555, 2024). "These inflammatory markers also correlate with SLEDAI-2K, levels of dsDNA (CCL2, CXCL10), the presence of lupus nephritis (CCL2, CXCL10, and TNF-α), and arthritis (IL6)." (PMID 38881906, 2024). "Plant extracts can alleviate the symptoms of arthritis by inhibiting the expression of inflammatory factors such as IL-6 and TNF-α in a rat ankle arthritis model." (PMID 39220949, 2024). "For example, Dnase2-/- mice develop a polyarthritis and induce high levels of TNF-α and IL-6 in affected joints, and blockade of TNF-α or IL-6 has a therapeutic effect on arthritis in Dnase2-/- mice." (PMID 39478149, 2024). "The inhibition of Hh signaling in rats with arthritis using cyclopamine, another inhibitor of Shh, reduced the expression of TNFα, IL-1β, and IL-6." (PMID 38668020, 2024).
Arthritis (continued). "In an arthritis mouse model, oral administration of P. gingivalis induced dysbiosis of the gut microbiota, increased IL-6 and CP production in serum, joint and intestinal tissues, and exacerbated joint destruction." (PMID 39619660, 2024). "TNF- α and IL-6 pro-inflammatory cytokine expressions were significantly increased when arthritis developed in all arthritic-induced rat groups compared to Normal control (P<0.05)." (PMID 39055869, 2024). "Conversely, the induction of arthritis in mice (model group) resulted in a significant increase in the levels of IL‐6, IL‐1β, and TNF‐α cytokines in the ankle joint tissue (p < .05)." (PMID 39554315, 2024). "The elevated serum IL-6 levels in patients with PsA were attributed to joint inflammation and increased PASI scores." (PMID 39429270, 2024). "A previous study found that CIA mice overexpressing SOCS3 had significantly reduced arthritis severity and IL-6 production." (PMID 38966637, 2024). "Synovial fluid samples collected 6 h after zymosan-induced arthritis were subjected to ELISA assays for determining their levels of IL-6." (PMID 39194751, 2024). "Syringic acid and p-coumaric acid have been reported to alleviate arthritis by inhibiting Il-6 inflammation and osteoclast formation, respectively, in a rat arthritis model." (PMID 39337919, 2024). "Knocking out WTAP in chondrocytes decreased the m6A level and significantly decreased the mRNA (ADAMTS4, ADAMTS5, MMP13, IL-6, IL-8, iNOS) and protein levels of arthritis-related genes (ADAMTS4, ADAMTS5, MMP13) in the OA cell model." (PMID 38172596, 2024). "PMB diminished the arthritis score, cell swelling, and IL-1β and IL-6 secretion in paws as well as combined CAIA model of A. actinomycetemcomitans infection." (PMID 39143049, 2024). "Considering that MSU-induced arthritis increases total peroxidaseand IL-1β and IL-6 levels, theseinflammatory markers were quantified at the end point of paw edemameasurement." (PMID 38991154, 2024). "IL-6/JAK/STAT signalling appears to have a central role in arthritis, where it is believed to drive recruitment, inflammation, and phenotypical changes in T-cells, B-cells and FLS." (PMID 37283752, 2023). "Along the same line, in the CIA model, the therapeutic intervention during the induction phase of arthritis with anti–IL-6 and anti–IL-21 reduced disease development more efficaciously than monotherapies." (PMID 37035302, 2023). "In contrast, BEVs administration in two mouse models for arthritis reduced serum levels of MCP-1 and IL-6 correlated with delays in the onset of arthritis and diminished cartilage pathology and bone marrow inflammation." (PMID 37344543, 2023). "We show that LXA4 reduced TNF-α, IL-1β, and IL-6 levels and increased IL-10 levels in TiO2-induced arthritis." (PMID 37388729, 2023). "We used self-reported arthritis as a measure to include anyone with RA symptoms and adjusted for individuals with self-reported arthritis as well as IL-6 levels in our analysis to account for potential confounding." (PMID 37874814, 2023). "Its expression is induced by proinflammatory factors such as LPS, tumor necrosis factor, and IL-6, as well as chronic inflammatory conditions like hepatitis, arthritis, and MS." (PMID 37409121, 2023). "Of note, isolated arthritis patients had a higher positivity of serum calprotectin and IL-6 (28.1% vs. 6.7% p = 0.02, 25.6% vs. 6.7% p = 0.04)." (PMID 38137631, 2023). "Oral consumption of PFE by osteoarthritic mice model significantly reduced inflammatory cytokines, and interleukin 6 (IL-6) and arthritis severity." (PMID 37333472, 2023). "In particular, in the CIA model, the knock-out of the IL-6 gene (IL-6−/−) led to complete protection from the onset of arthritis and a decrease of the anti-collagen type II autoantibody level." (PMID 37035302, 2023).
Arthritis (continued). "The clusters were #0 Tripterygium wilfordii, #1 clinical trial, #2 toxicity, #3 synoviocytes, #4 angiogenesis, #5 glomerulonephritis, #6 collagen-induced arthritis, #7 apoptosis, #8 migration, #9 interleukin-6 #10 T-cells, and #11 anti-inflammation." (PMID 38013265, 2023). "These antibodies enhanced the adhesion between OPN and FLSs, increased the expression of inflammatory cytokines including IL-6, aggravated arthritis, and lowered the retention rate of TNF inhibitors in RA patients." (PMID 36804906, 2023). "Several studies reported that LMT-28 played a crucial role in the improvement of inflammation in collagen-induced arthritis by inhibiting the IL-6/GP130 signaling pathway." (PMID 36643585, 2023). "HlSerpin-a suppressed the production of pro-inflammatory cytokines TNF and IL-6 by LPS-stimulated macrophages and dendritic cells and relieved inflammation in a murine arthritis model." (PMID 36756125, 2023). "To further assess the severity of arthritis, we measured the mRNA levels of a variety of pro-inflammatory cytokines and chemokines, including Il18bp, Il18, Il1b, Il6, Il1r2, Ifng, Cxcl9, Cxcl1, and Cxcl2 in arthritic joints of IL-18BP KO and WT littermates." (PMID 37415987, 2023). "Fenofibrate, a PPAR-alpha ligand, has been shown to inhibit the development of arthritis in a rat model of human RA by reducing cytokine production (IL-6, IL-8 and granulocyte monocyte colony-stimulating factor) from FLS." (PMID 36937015, 2023). "The first PCT application focused on the API (specific monoclonal antibody), compositions and medical indication (method of treatment and use claims) for an IL-6-mediated disease or disorder, e.g., arthritis." (PMID 38126073, 2023). "The serum level of one of the main cytokines for the arthritis IL-6 rises from midnight and reaches the peak level in the early morning in healthy control." (PMID 37569682, 2023). "When serum levels of TNF-α, IL-1 β, and IL-6 were examined in arthritis and normal control rats, there was a significant rise in given proinflammatory cytokines in arthritic disease rats (P < 0.001)." (PMID 37520245, 2023). "YH23537 improved joint histopathologic scores and reduced IL-1β and IL-6 expression in OA joints in MIA-induced arthritis rats." (PMID 37159594, 2023). "The neutralization of Gal-9 decreased the secretion of MCP-1 and IL-6 in arthritis synovial cultures, dominated by FLSs." (PMID 36672263, 2023). "In animal models of arthritis tofacitinib treatment has led to decreased levels of circulating IL-6, IL-8, CCL2, and CXCL10." (PMID 36124688, 2022). "Gavage with daily 75 mg/body weight (BW) cinnamaldehyde significantly reduced the severity of arthritis, bone erosion and destruction, as well as the level of serum IL-6 induced by collagen in rats." (PMID 36428337, 2022). "IL-6 plays an important role in the differentiation of B lymphocytes into auto-antibody producing plasma cells, which are involved in the pathogenesis of arthritis by immune complex (IC) formation." (PMID 35566047, 2022). "In the AIA rat model of arthritis, celastrol treatment (3 g/kg/day) suppressed the expression of the proinflammatory cytokines IL-6, IL-17, and IFN-γ, reduced MMP-9 activity, and reduced serum levels of anticyclic citrullinated peptide (aCCP) antibodies." (PMID 35631330, 2022). "For example, high levels of IL-18 and IL-1β are detected in systemic disease; high levels of IL-6 and TNFα, in arthritis; and high levels of IL-1β and IL-6, in fever and skin rash, respectively." (PMID 36090971, 2022). "Cytokines level (members of IL-1 family, IL-6 and its receptor, IL-17, IL-20, IL-21, and IL-23) increases in early stages of arthritis and decreases during regression of inflammation." (PMID 35061737, 2022). "Two particularly important proinflammatory cytokines in arthritis are IL-6 and IL-8, both activated by NF-κB-dependent mechanisms." (PMID 35459919, 2022).
Arthritis (continued). "Administration with cinnamaldehyde (75 mg/kg BW per day) was also noticed to reduced serum RANKL and IL-6 levels in rats apart from remission collagen that induced the severity of arthritis and bone destruction." (PMID 36428337, 2022). "Clinical arthritis scores and the expression levels of proinflammatory cytokines (e.g., IL-17, IL-1β, IL-6, and TNF-α) were significantly attenuated in p40-EBI3-overexpressing and p40-EBI3-Fc-treated mice with CIA compared to vehicle-treated mice with CIA." (PMID 34782759, 2022). "Joint swelling and the arthritis-related expression levels of IL-1β, IL-6, RANKL, MMP9, and OC-Stamp were strongly reduced, while Foxp3 was induced." (PMID 36003376, 2022). "In a rat model of arthritis induced by type II collagen and treated with DAPs, IL-1β, IL-2, IL-6, TNF-α, IFN-γ, and dihydroorotate dehydrogenase (DHO-DHase) were inhibited." (PMID 36235835, 2022). "We used a mouse model of adjuvant-induced arthritis, and at early time-points of the experiment, levels of “classical” pro-inflammatory cytokines, such as IL-1β, IL-6, and TNF, were measured." (PMID 36293292, 2022). "Mice lacking CRY1 and CRY2 have increased levels of activated T cells, and when arthritis was induced in these mice, serum IL6 levels were higher than in wild type mice with induced arthritis." (PMID 35886000, 2022). "To determine the role of IL-6 in the development of arthritis, we treated 6-wk-old DNase II−/−STINGS365A/S365A mice with a neutralizing antibody against the IL-6 receptor (anti–IL-6R) once a week." (PMID 34901991, 2022). "The research was inspired by the evidence that IL-6 is a key cytokine supporting chronic inflammatory diseases and the potential progression of their outcome (e.g., arthritis and other immune-system mediated diseases)." (PMID 35625609, 2022). "T cell trafficking and proinflammatory cytokines such as TNF-α, IL-1β, IL-6, and MMPs are reduced when IL-7 is blocked, which lowers joint inflammation." (PMID 35368757, 2022). "It would be plausible that inflammatory stimuli such as TNF-α, IL-1, and IL-6, all induced during K/B×N serum–transferred arthritis, promote sPLA2-IIA expression in these leukocytes, leading to increased circulating sPLA2-IIA concentrations in this model." (PMID 35076027, 2022). "Imperatorin is used to treat arthritis as it reduces the levels of interleukin (IL)-1β, IL-6, and tumor cell necrosis factor-α inflammatory factors." (PMID 36435778, 2022). "Dihydroartemisinic acid (DHA), an ATM derivative, reduced inflammation in a rat arthritis model by downregulating Interleukin-6 (IL-6)." (PMID 36431766, 2022). "In accordance with our finding, it has been previously observed that tofacitinib treatment leads to a marked decrease in circulating IL-6 levels in RA patients and in animal models of arthritis." (PMID 36124688, 2022). "Interleukin (IL)-1 inhibitors are largely employed in patients with Still’s disease; in cases with refractory arthritis, IL-6 inhibitors have shown to be effective on articular inflammatory involvement." (PMID 36619631, 2022). "Blocking TNF-α or IL-6 signaling using neutralizing antibodies alleviated arthritis manifestations in DNase II−/−STINGS365A/S365A mice." (PMID 34901991, 2022). "Using the adjuvant-induced arthritis (AIA) model in rats, the positive effect of local cryotherapy on arthritis severity and joint damage was shown to be IL-6/IL-17A-driven but TNF-α independent." (PMID 35488311, 2022). "NPnon-targeted treatment suppressed pro-inflammatory cytokines IL-6 by 73.3% when compared to arthritis control (p-value: 0.03); TNF-α by 42% p-value: 0.002; IL-17A by 70.6%, p-value: 0.05; and IFN-γ by 61.3%, p-value: 0.03) pg/mL." (PMID 36241847, 2022). "At the acute inflammatory phase of arthritis, an increase in pro-inflammatory cytokines occurred in aortas as attested by the increased mRNA expression of IL-6, TNF-α, and CXCL-1 (the IL-8 murine equivalent) in AIA." (PMID 35488311, 2022).